BRAF (B-Raf proto-oncogene, serine/threonine kinase)
Diseases named in the same sentence as BRAF in open-access papers (continued):
Sharing a sentence is not in itself a finding about the gene and the disease.
melanoma (continued). "On the one hand, in patients with stage III and stage IV melanomas, the presence of BRAF mutation has been shown to be associated with a worse outcome compared to patients with BRAF wildtype melanomas." (PMID 35192052, 2023). "We applied scMemorySeq to BRAF V600E mutated WM989 melanoma cells containing the drug-susceptible and primed states." (PMID 37932277, 2023). "Three BRAF kinase inhibitors, vemurafenib, dabrafenib, and encorafenib, have been approved as a treatment for melanoma patients carrying the BRAF V600E mutation." (PMID 38136350, 2023). "Our data show that in daily clinical practice, comorbidities and geographical region are significantly associated with receiving adjuvant BRAF/MEK-inhibition therapy or adjuvant anti-PD-1 systemic treatment in patients with resectable stage III melanoma." (PMID 36672358, 2023). "In this study, we demonstrated that TFEB exerts a relevant impact on the behaviour of BRAF-mutated melanomas." (PMID 37160873, 2023). "In conclusion, HPF was shown to be a potent natural compound able to hinder the expression and function of different key proteins involved in pro-survival and pro-metastatic signaling of BRAF-mutated melanoma cells." (PMID 36674794, 2023). "Because BRAF-mutated melanomas are addicted to the Mitogen Activated Protein Kinase (MAPK) pathway they show a high response rate to BRAF and MEK inhibitors." (PMID 37296851, 2023). "Meanwhile, transcription factor SOX10 diminished expression leads to acquisition of low proliferative phenotype that is associated with resistance of BRAF‐mutant melanoma cells to BRAF inhibitors." (PMID 36533319, 2023). "BRAF mutations are prevalent in CLs derived from melanoma and colorectal cancers, and NRAS in melanoma, leukemia, bladder cancer, and lymphoma." (PMID 37830744, 2023). "The cancer cell fraction estimated for the primary melanoma sample is consistent with fraction estimated using the mutant allele frequency for BRAF V600E, the presumed initiating oncogene." (PMID 37932252, 2023). "Another example is vemurafenib (PLX4032 and RG7204), a selective BRAF serine–threonine kinase inhibitor inducing autophagy, which is employed in the treatment of advanced melanoma with a BRAF gene mutation (IC50 = 31 nM)." (PMID 38203445, 2023). "NF1 mutations are prevalent in melanomas that are wild-type for BRAF and NRAS, NF1 are considered driver mutations in these patients." (PMID 37762707, 2023). "Around 50% of the patients with melanoma have a mutation in the Ser/Thr-Kinase BRAF (most of the time V600E)." (PMID 36831417, 2023). "Taken together, these data suggest that BRAF alteration in melanoma brain metastases is associated with decreased TAB and worse survival outcomes." (PMID 37589977, 2023). "The co-occurrence of BRAF or NRAS mutations with TERT promoter mutations was also prognostic for poor disease-free survival in multivariate analyses in primary melanoma." (PMID 37418389, 2023). "For example, somatic mutations in the V600 codon of the BRAF oncogene (i.e., BRAF V600E or V600K) occur in as many as 50% of melanomas, consistent with data indicating that these oncogenic driver mutations promote cell proliferation and carcinogenesis." (PMID 37169747, 2023). "Non-V600 BRAF mutations have occasionally been reported in melanomas and they account for approximately 11% of melanomas." (PMID 37627054, 2023). "Mutations in the BRAF gene occur in 40–85% of melanoma cases, with the lowest frequency in primary, an increase in metastatic sites and the highest in recurrent melanomas." (PMID 36765875, 2023). "BRAF + MEK inhibitors have been used for many years in other BRAF-mutated solid tumors, mainly melanoma and non-small cell lung carcinoma (NSCLC)." (PMID 37435488, 2023). "About 8% of all human cancers have BRAF mutations; these mutations are more common in melanomas (40–70%), thyroid (36–53%), and colorectal (5–22%) carcinomas." (PMID 37240450, 2023).
melanoma (continued). "In contrast to melanoma, where V600E represents the majority of BRAF mutations, in NSCLC, V600E mutations represent only approximately half of the cases, whereas the other half is composed of other mutations, collectively named non-V600E." (PMID 37999148, 2023). "Another recent study identified a novel LRRFIP2-RAF1 fusion in wild-type BRAF acral melanoma with a concomitant KIT variant." (PMID 38111008, 2023). "Melanoma cells, which contain mutated BRAF and are resistant to the BRAF inhibitor PLX4720, exhibit increased oxidative metabolism and mitochondrial dependence for survival." (PMID 36959802, 2023). "In three BRAF-mutated melanoma cell lines, we provided evidence that HPF induces HO-1 expression and influences the expression of other proteins involved in iron homeostasis, cell invasion, and metastatic potential." (PMID 37507910, 2023). "More than half of melanoma patients have a BRAF mutation, and 90% of them have a BRAF(V600E) mutation." (PMID 37760480, 2023). "Currently, immunotherapy with anti‐PD‐1 blockade and dual‐targeted therapy with Dabrafenib plus trametinib (D + T) target therapy have been approved as adjuvant therapies for Stage III melanoma with BRAF V600 mutation." (PMID 37016119, 2023). "In fact, our first medical successes with those MAPK-pathway-targeted therapies were evidenced in melanomas bearing BRAF mutations, where BRAFi demonstrated early responses in monotherapy." (PMID 36831610, 2023). "Melanoma, especially BRAF-mutated melanoma, is still a high-mortality tumor type and the currently available therapies do not provide solutions." (PMID 36674794, 2023). "BRAF mutations are present in 80% of melanoma mutations, so targeting the BRAF gene is an important strategy for melanoma treatment." (PMID 37532809, 2023). "One of the ways for metastatic melanoma cells to survive and develop cancer in the brain environment is the presence of oncogenic BRAF mutation, which occurs in up to 50% of metastatic melanoma cases." (PMID 37627116, 2023). "The genetic underpinning of melanoma was established by identification of somatic BRAF and germline CDKN2A mutations in cutaneous melanoma and familial melanoma, respectively." (PMID 37841001, 2023). "Recent data showed that TERT promoter mutations, in BRAF-mutant melanoma cell lines, were associated with sensitivity to BRAF and MEK inhibitors highlighting a link between the expression of telomerase and sensitivity to targeted therapy." (PMID 37296851, 2023). "Evidence showed that patients with BRAFV600E-mutated melanoma were more likely to have CNS involvement than those with BRAF wild-type melanoma." (PMID 37920169, 2023). "Melanoma that develops in body regions exposed to sunlight is more likely to have the BRAF gene mutation (V600E)." (PMID 37102943, 2023). "The pharmacological efficacy of BRAF inhibitors is limited to a subset of cancer patients with BRAF-mutated metastatic melanoma, because the durability of responses in BRAF-mutated melanoma is restricted by the onset of drug resistance mechanisms." (PMID 37446932, 2023). "The preceding data suggest that AKT2 differentially promotes the metastatic potential of melanomas, but to address the mechanism, we utilized a set of human melanoma cell lines driven by mutation in BRAF, as well as by PTEN loss." (PMID 37894325, 2023). "This includes in patients with liver metastases, uveal melanoma, mucosal melanoma and BRAF-mutated melanoma and represents the majority of patients with melanoma." (PMID 37072748, 2023). "In this study, data on melanoma samples with BRAF V600E mutation (BRAF V600E-mutant melanoma) and melanoma samples with wild-type BRAF V600E alleles (BRAF V600E WT melanoma) were collected from The Cancer Genome Atlas (TCGA) database." (PMID 36704723, 2023). "Further, in BRAF-mutated melanoma, targeted therapy has been shown to have a high response rate, up to 100%." (PMID 37444454, 2023).
melanoma (continued). "Vemurafenib was first introduced 2008 as an oral selective inhibitor of oncogenic B-Raf kinase against melanoma harboring BRAF V600E mutation." (PMID 37568193, 2023). "We used The Genotype-Tissue Expression (GTEx) database (n = 1305) for the analysis of non-cancerous patient skin samples and The Cancer Genome Atlas (TCGA) database (n = 366) for the analysis of NRAS- and BRAF-mutated melanoma patient samples." (PMID 37235843, 2023). "Our study shows that miR-195-5p antitumoral activity can be spread to bystander cells through EVs, improving melanoma response to targeted therapy and revealing a promising EV-based strategy to increase clinical response in patients harboring BRAF mutations." (PMID 37174717, 2023). "BRAF-targeted therapies are widely used for the treatment of melanoma patients with BRAF V600 mutations." (PMID 37834222, 2023). "Many melanomas carry gain-of-function mutations in the v-RAF murine sarcoma viral oncogene homolog B1 (BRAF), which functions in cell division and differentiation and is treatable with a BRAF inhibitor (BRAFi) in these cases." (PMID 36860271, 2023). "BRAF/MEKi also led to a favourable response for BRAF-mutated melanoma in a Japanese population who relapsed after PD1 failure." (PMID 37093349, 2023). "While BRAF (mainly BRAF V600E) is a well-known oncogenic variant involved in various cancers, such as melanoma and papillary thyroid cancer, in sporadic MTCs, BRAF V600E has rarely been reported and appears to be a distant marginal driver." (PMID 37835559, 2023). "The WNT–β-catenin signaling pathway is a key driver in the initiation and progression of CRC, differentiating it from other cancers, including BRAF-mutated melanoma." (PMID 36759733, 2023). "The current research explores BRAF mutation-related biological features in melanoma and establishes a prognostic signature." (PMID 37205993, 2023). "BRAF/MEK inhibitor combined strategies, including dabrafenib plus trametinib and encorafenib plus binimetinib, benefit advanced melanoma patients with BRAF gene mutations." (PMID 38104104, 2023). "Several Canadian and international studies have reported melanoma treatment patterns and outcomes, but these studies have been limited in their reporting on multiple lines of therapy or on BRAF mutation status." (PMID 37185430, 2023). "The treatment strategy for BRAF-mutated melanoma remains unsatisfactory, although the advent of immune checkpoint inhibition has improved the prognosis of advanced melanoma." (PMID 36995534, 2023). "With the BRAF gene being the most commonly mutated gene in melanoma, the BRAF subtype has the highest occurrence rates." (PMID 36865793, 2023). "For example, Vemurafenib targets the BRAF mutation in advanced melanoma, Trastuzumab targets Her2 in breast cancer, and Crizotinib targeting the ALK mutation in non-small cell lung cancer, among others." (PMID 37217528, 2023). "In 10% of the instances with radial growth and in 6% of in situ melanomas, BRAF mutations are less frequent in early-stage melanoma." (PMID 37102943, 2023). "A precision medicine approach to BRAF-mutated melanoma has demonstrated potential to improve health outcomes; however, factors inherent to precision medicine and LA’s healthcare systems create significant implementation obstacles." (PMID 36998456, 2023). "The results of the present work confirm and extend these findings by demonstrating that GALC overexpression increases the tumorigenic potential of both A2058 and A375 human melanoma cells harboring the tumor-driving BRAF(V600E) mutation." (PMID 37445731, 2023). "Given the high frequency of BRAF mutations, targeted BRAF inhibitors (BRAFis), such as vemurafenib and dabrafenib, were developed for advanced melanoma therapy; however, patients treated with a BRAFi eventually experience drug resistance." (PMID 36854755, 2023).
melanoma (continued). "Adjuvant treatment with immune checkpoint inhibitors like PD1-antibodies (ICI) ± CTLA4-antibodies (cICI) or targeted therapy with BRAF/MEK inhibitors (TT) in high-risk melanoma patients demonstrate a significant improvement in disease-free survival (DFS)." (PMID 37405475, 2023). "BRAFwt/NRASwt patients have decreased melanoma-specific survival compared to those with NRAS or BRAF mutations." (PMID 36909026, 2023). "Greater than 50% of melanomas contain a mutation in the BRAF gene, which encodes a protein kinase involved in RAS/MAPK signaling that is important for cellular proliferation." (PMID 37142570, 2023). "Melanoma frequently harbors BRAF, NRAS, or KIT mutations which influence both tumor development and treatment strategies." (PMID 37403699, 2023). "This same group of kinases was found to have increased activity in vemurafenib-resistant melanoma harboring BRAF V600E mutations." (PMID 37760447, 2023). "Targeted therapies that inhibit this pathway, such as BRAF inhibitors, have been developed to treat melanoma and other cancers that have activating mutations in this pathway." (PMID 37504268, 2023). "The first discovery of the BRAF V600E mutation in 2022 by Dr. Garraway and Dr. Chin, and later on, its significance in melanoma treatment has been a major breakthrough in this field of oncology." (PMID 37504268, 2023). "Although melanoma with BRAF mutation is considered to be a more aggressive disease than its wide‐type, therapeutic approaches targeting BRAF V600E/K were the first and most successful precise treatment of melanoma so far." (PMID 37016119, 2023). "Oncogenic BRAF mutations were found in different types of human cancers, including melanoma, colorectal cancer, papillary thyroid carcinomas, ovarian cancer, and NSCLC." (PMID 37111737, 2023). "Vemurafenib (PLX4032) and dabrafenib (GSK2118436), small-molecule mutant BRAF kinase inhibitors, are used to treat melanoma patients diagnosed with the BRAFV600 mutation." (PMID 36765875, 2023). "The BRAF gene mutation correlates to melanoma patients' prognosis, and therefore, further investigation of signaling pathways and genes perturbed by BRAF is necessary." (PMID 37205993, 2023). "Treatment with recombinant exogenous IGFBP7 human melanoma cell lines carrying mutated BRAF can induce cell senescence and apoptosis, and systemically administrated in xenograft mouse models counteract melanoma growth." (PMID 37762344, 2023). "The combination treatment of fisetin and sorafenib significantly inhibited the migration and invasion of BRAF-mutated melanoma cells both in vitro and in vivo and reduced the expression of EMT-inducing transcription factors." (PMID 36829966, 2023). "Patients with melanomas harboring a BRAF mutation (BRAFMut) have a worse prognosis than those with wildtype (BRAFWT) tumors." (PMID 36539575, 2023). "In the BRAF V600+ subset (N = 19), melanoma driver gene mutations and CNVs were higher in tumors from NR than those from R, suggesting a genetic mechanism promoting tumor escape from TT, although the difference was not statistically significant." (PMID 36901733, 2023). "In patients with advanced melanoma, lower basal levels of BRAF V600E ctDNA were significantly associated with longer OS and PFS than higher basal levels." (PMID 37627054, 2023). "The BRAFV600E inhibitor vemurafenib has shown only modest efficacy as monotherapy in BRAF-mutated mCRC relative to melanoma carrying BRAFV600E mutation due to the development of primary or secondary resistance." (PMID 37106808, 2023). "Atx PA and Atx LF have shown interesting intrinsic anti-tumor properties because they inhibit MAPKK-associated pathways, for example, in melanoma bearing the V600E BRAF mutation and in melanoma xenografts by killing endothelial cells." (PMID 37446406, 2023). "BRAF-mutated melanoma has different clinical characteristics and is associated with a more aggressive bioactivity than BRAF wild-type (WT) melanoma." (PMID 37629523, 2023).
melanoma (continued). "The function of EZH2, particularly in BRAF-mutated melanoma and in the emergence of resistance to targeted therapies, was incompletely understood." (PMID 36768289, 2023). "There is evidence supporting that mutational inactivation of STAG2 is a major cause of the resistance of BRAF-mutant melanomas to BRAF/MEK inhibitors." (PMID 37479689, 2023). "Since after PTEN loss, melanoma rapidly forms in melanocyte-targeted BRAF-mutated mouse models, it was suggested that PTEN is a pivotal factor in maintaining the growth arrest of nevi." (PMID 36834954, 2023). "Genetic markers indicating favorable ICI responders in melanoma include high tumor mutational burden, BRAF wild type, and increased gene expression of inflammation and T-cell population." (PMID 37239381, 2023). "Mutations in genes involved in the MAPK pathway are most common in melanoma with changes in mitochondrial function, including activating mutations in the BRAF gene, NRAS gene and tyrosine kinase (such as KIT) and inactivating mutation in the NF1 gene." (PMID 37221594, 2023). "The advent of targeted therapies and immunotherapy in the adjuvant and neo-adjuvant settings brings new issues such as which treatment should be favored in the context of BRAF mutated melanomas." (PMID 37936607, 2023). "BRAF mutations are highly prevalent in melanomas and nevi, with more than 80% of cases exhibiting these mutations." (PMID 38021761, 2023). "Recently, overexpression of yes-associated protein (YAP) was found to be associated with resistance to BRAF inhibitors in melanoma." (PMID 36694209, 2023). "The Cancer Genome Atlas classifies the genome mutations that occur in melanoma into four subtypes: mutant BRAF, mutant NRAS, mutant NF1, and triple-wild-type." (PMID 37445615, 2023). "Clinical phase III trials like the BRIM-3 trial, BREAK-3, COMBI-d, COMBI-v, and COLUMBUS are significant examples on the full list of trials focused on the treatment of melanoma with the BRAF V600E mutation." (PMID 37504268, 2023). "About 50% of UV-related melanomas harbor BRAF mutations, with valine (V) to glutamic acid (E) substitution in codon 600 (p.V600E) being the most common mutation." (PMID 37239381, 2023). "As the most frequently mutated gene in cutaneous melanoma, BRAF has become a popular target for melanoma treatment." (PMID 37239381, 2023). "Adjuvant dual BRAF and MEK inhibition has previously been shown to be effective and well-tolerated in stage IV BRAF-mutated melanoma." (PMID 37444454, 2023). "One of the most common mutations in primary melanoma inhibitors is BRAF mutation, found in 50–60% of metastatic cases; thus, some of the first targeted agents to be developed were BRAF inhibitors." (PMID 36900136, 2023). "Consistently, inhibition of BRAF or MEK1/2 increases oxidative phosphorylation and mitochondrial biogenesis in BRAF-mutated melanoma cells through MITF and PGC1α upregulation." (PMID 37834284, 2023). "In accordance, we found in our cohort of BRAF-mutated patients that most melanomas (85%) presented a mutation in the TERT promoter, the most frequent being −124C > T (50%) followed by −146C > T (28%) and by −138/−139CC > TT (7%)." (PMID 37296851, 2023). "A recent experimental study demonstrated that gene expression in melanoma cells reversed during treatment holidays, causing the cells to re-sensitize to a BRAF inhibitor rechallenge." (PMID 36952376, 2023). "In BRAF-mutated melanoma, the presence of chronic ER stress leads to ISR activation by enhancing P-eIF2α expression and contributes to chemoresistance through a dysregulation of autophagy." (PMID 37601686, 2023).